TNF (tumor necrosis factor)
Diseases named in the same sentence as TNF in open-access papers (continued):
Sharing a sentence is not in itself a finding about the gene and the disease.
colorectal cancer (continued). "Celastrol was demonstrated to decrease interlukein-6 (IL-6) secretion and gene expression via downregulation of NF-κB in prostate carcinoma PC-3 cells, and inhibit colorectal cancer cell growth and migration through the suppression of tumor necrosis factor alpha (TNF-α) expression and IL-1b protein." (PMID 32041250, 2020). "Moreover, our group has previously shown that TNF-β induces cancer progression and thus stimulates colorectal cancer cell malignity with the same potency as TNF-α." (PMID 32244288, 2020). "Thus, it was plausible that Sur-X induced a rapid and transient secretion of TNF-α by colorectal cancer cells and subsequently activated NF-κB signaling pathway for a short time." (PMID 32381104, 2020). "Moreover, mechanistic studies have established that IL-1β, IL-6, and TNFα are involved in colorectal cancer progression and that expression of these cytokines is regulated by vitamin D." (PMID 32425932, 2020). "Interestingly, the most significant increase of TNF-α secreted by colorectal cancer cells was observed after the treatment of Sur-X for 30 min." (PMID 32381104, 2020). "Furthermore, adipocytes also can produce polypeptide hormones (e.g., adiponectin and leptin), TNF-α, IL-6 and free fatty acid to mediate inflammatory response in colorectal cancer." (PMID 31963221, 2020). "Additionally, KLTi inhibits tumor necrosis factor-alpha- (TNF-α-) mediated epithelial mesenchymal transition (EMT) in colorectal cancer cell lines by inhibiting the NF-κΒ signaling pathway." (PMID 32047528, 2020). "We have reported that TNFα decreases CLDN4 expression in colorectal cancer." (PMID 31040910, 2019). "Therefore, we examined 6 common cytokines (IL-1β, IL-2R, IL-6, IL-8 IL-10 and TNF-α) and found colorectal cancer derived HT29 and SW480 cells expressed IL-8 and further increased after irradiation." (PMID 31706322, 2019). "A chemokine panel was used to screen plasma samples from patients with colorectal cancer, and five chemokines and four cytokines identified as associated with increased total mortality, among which TNF-α and CCL24 were exclusively associated with colorectal cancer-specific mortality." (PMID 31836011, 2019). "The role of TNFα has also been confirmed in other tissues, including malignant tumors, such as tongue cancer, laryngeal carcinoma, cholangiocarcinoma, thyroid cancer and colorectal cancer." (PMID 30157906, 2018). "TNFα is destructive to tumor blood vessels and induces cell death by necrosis at high concentrations while elevated levels of IL-6 are also present in numerous tumors such as colorectal cancer, gastric carcinoma, and Hodgkin lymphoma." (PMID 30622433, 2018). "Based on these findings, we believe that the Gal-3/TNF-α ratio could be a predictor for the advanced stages of colorectal cancer." (PMID 29849497, 2018). "The association between TNF-α -308 G>A polymorphism and colorectal cancer (CRC) is not fully understood, especially the connections between TNF-α -308 G>A polymorphism and clinical features of CRC." (PMID 28575042, 2017). "4-HNE and TNFα contribute to the initiation of colorectal cancer as diffusible mediators of MIBE." (PMID 29254234, 2017). "Recently it has been established that the distal region of the PUMA promoter contains NF-kB p65 binding sites and in colorectal cancer cells canonical NF-kB p65 signaling via TNF-alpha induction could promote PUMA gene transcription." (PMID 28099441, 2017). "Furthermore, the expression of immune cell-derived TNFα has recently been recognized as the most important predictor of the positive anti-tumor response attributed to TNFα in colorectal cancer." (PMID 27662661, 2016). "The effect of less common TNF-α-308A allele on the risk of colorectal cancer was also not found to be significant (p value = 0.175)." (PMID 27331018, 2016). "The overall association between the TNF-α-308G/A SNP and the modulation of the colorectal cancer risk in the population under study was found to be non-significant (p > 0.05)." (PMID 27331018, 2016).
colorectal cancer (continued). "Macrophages are critical source of TNFα and, in particular, macrophages that infiltrate the tumor and circulate in colorectal cancer patients are identified as pro-inflammatory, being able to mediate tumor cell killing by the antigen-driven secretion of both IL-6 and TNFα." (PMID 27662661, 2016). "The serum levels of inflammatory factors, including TNF-α, IL-8, and IL-6 are elevated in colorectal carcinoma patients, and it has been suggested that increased plasma levels of these cytokines may have a prognostic role." (PMID 26087180, 2015). "Overall and group-specific summary statistics for TNF-a 308, TNF-a 238 in colorectal cancer." (PMID 24404201, 2014). "The pro-inflammatory cytokines TNFα and IL-17 may contribute to this effect by stimulating glycolysis and growth factor production in colorectal cancer cells." (PMID 23866118, 2013). "Our presurgical analysis shows that some cytokine levels (IL-6, IL-8, IL-1β and TNFα) were significantly higher in plasma of patients affected by colorectal cancer compared to healthy donors and these differences progressively increase in advanced tumor stages." (PMID 24040252, 2013). "The present results show that TNFα and IL-17 synergistically stimulate glycolysis and growth factor production by human colorectal cancer cells, effects that could contribute to the positive effect of inflammation on carcinogenesis." (PMID 23866118, 2013). "In addition, IGF-1R activates the extracellular signal-regulated kinase (ERK) and nuclear factor-κB (NF-κB) pathway that protect colorectal carcinoma cells from tumor necrosis factor-α (TNFα) induced apoptosis." (PMID 24182354, 2013). "TNF can induce tissue remodeling and stromal development, which are required for tumor growth and spread, and its expression is enhanced in various types of cancers including ovarian, breast, prostate, and bladder, and colorectal cancers." (PMID 24212934, 2011). "There is no information about the relationship between the TNFα -1031 T/T polymorphism and colorectal cancer and further studies are necessary to confirm above results." (PMID 18433468, 2008). "Other polymorphisms were also investigated within the TNFα promoter region of the gene (-857 C/T, -308 G/A, -238 G/A) and they appeared to confer no protective influence on colorectal cancer risk, a finding which is consistent with other observations." (PMID 18433468, 2008). "In conclusion, it appears that independently both the TNFα-1031T/T and the NOD2 3020insC polymorphisms may act as low risk modifiers of colorectal cancer risk." (PMID 18433468, 2008). "Ten SNPs in the following six genes: NOD2 (2140 C/T, 2722 G/C), DLG5 (113 G/A), OCTN1 (1672 C/T), OCTN2 (-207 G/C), IL4 (-590 C/T) and TNFα (-308 G/A, -857 C/T, -863 C/A, -1031 T/C) were screened in a consecutive series of colorectal cancer patients using a two-staged approach." (PMID 18433468, 2008). "The original work had shown a suppression of CMI-associated cytokines, tumour necrosis factor-α (TNF-α) and interferon-γ (IFN-γ) in patients with colorectal cancer that was greater in those with a Dukes’ C tumour compared to those with either a Dukes’ A or B tumour and was reversed by surgery." (PMID 16641913, 2006). "We have investigated the secretion of interferon alpha (IFN-alpha), IFN-gamma, interleukin-1alpha (IL-1alpha), IL-1beta, IL-2 and tumour necrosis factor alpha (TNF-alpha) in whole blood cell cultures (WBCCs) of colorectal cancer patients upon mitogen stimulation." (PMID 9792144, 1998). "Whereas the values for IL-1beta and TNF-alpha remained virtually unchanged in comparison with healthy control subjects, WBCCs of colorectal cancer patients secreted significantly lower amounts of IFN-alpha (P < 0.005), IFN-gamma (P < 0.0001), IL-1alpha (P < 0.0001) and IL-2 (P < 0.05)." (PMID 9792144, 1998).
colorectal cancer (continued). "Given the established role of TNF-α in promoting inflammatory responses and modulating apoptotic sensitivity in colorectal cancer, these results suggest that the anti-inflammatory properties of statins may contribute to their reported chemopreventive effects in this malignancy." (PMID 41596561, 2026). "Next, we investigated whether TNF-α modulates ferroptosis in colorectal cancer cells." (PMID 40695795, 2025). "However, the detailed molecular mechanisms by which TNFα-mediated ATP release enhances antitumor immunity in colorectal cancer are still unknown." (PMID 38195677, 2024). "Furthermore, it has been demonstrated that long-term intake of FaOH and FaDOH downregulates the gene expression of cyclooxygenase-2 (COX-2) as well as the inflammatory cytokines interleukin (IL)-6 and tumor necrosis factor α (TNFα) in the colonic epithelium in a rat model of colorectal cancer (CRC)." (PMID 38068860, 2023). "Moreover, TNF-α is highly correlated with colorectal cancer." (PMID 36225358, 2022). "Therefore, anti-TNF was chosen as the entry point of colorectal cancer prevention in our study." (PMID 36618924, 2022). "Chronically elevated COX-2 levels correlate with increased risk for colorectal adenocarcinomas, and the use of chronic nonsteroidal anti-inflammatory drugs and administration of TNFα blocking antibodies have been associated with a decreased risk of developing colorectal cancer." (PMID 33540543, 2021). "In a colitis-associated colorectal cancer model using periostin-/- mice, lack of periostin expression resulted in fewer inflammatory peritoneal macrophages, as evidenced by a reduced expression of TNF-α and IL-1β, and up-regulation of TGF-β and IL-10." (PMID 33466303, 2021). "Interestingly, Faecalibacterium prausnitzii and its supernatant could also regulate the expression of IL-10 and TNF-α, and then inhibit load of colorectal cancer." (PMID 32272885, 2020). "In this study, we show that 4-HNE and TNFα produced by M1-polarized macrophages are mediators that can activate Wnt/β-catenin signaling and potentially induce dedifferentiation of colon epithelial cells as a novel mechanism for commensal-initiated colorectal cancer." (PMID 29254234, 2017). "Additionally, a genetic link between TNF-α and colorectal cancer has been identified recently." (PMID 28492497, 2017). "Finally, TNF may also enhance metastasis by promoting epithelial to mesenchymal transition (EMT) in colorectal cancer." (PMID 28492497, 2017). "However, since the sample size of Eastern populations is relatively small, the association between TNF-a 308A and risk of colorectal cancer was not significant." (PMID 24404201, 2014). "In this article, we gathered data from all previous studies of TNF-α polymorphisms and colorectal cancer, and a meta-analysis containing 3372 cases and 4523 controls was conducted to investigate whether TNF-α 308, TNF-α 238 promoter polymorphisms were associated with the risk of colorectal cancer." (PMID 24404201, 2014). "CKT manufactured TCR-T cells demonstrated higher 4-1BB upregulation, IFN-γ, TNF, and granzyme B (GZMB) production, and enhanced killing of pancreatic and colorectal cancer cell lines in 2D and 3D tumor spheroid co-culture." (PMID 42220480, 2026). "Our data demonstrate that QFG downregulates TNF-α, IL-6, and NF-κB expression in colon tissue, which is consistent with previous studies showing that QFG inhibits pro-inflammatory signaling in colorectal cancer." (PMID 40883855, 2025). "Our results showed that the concentrations of IL‐6, TNF‐α, and TGF‐β1 in the serum of NSD2fl/fl‐Vil1‐Cre mice with colorectal cancer were much lower than those in the serum of WT mice." (PMID 38400589, 2025). "In both cell lines, TNF-α treatment rapidly closed the wound compared with the controls (p < 0.0001), and this result demonstrated the role of TNF-α induced EMT in colorectal cancer cases." (PMID 40558596, 2025).
colorectal cancer (continued). "In colorectal cancer, açaí decreased myeloperoxidase (MPO) and cytokines such as tumor necrosis factor alpha (TNF-α), interleukin 1 beta (IL-1β) and interleukin 6 (IL-6), and inhibited cyclooxygenase 2 (COX-2), also reinforcing its anti-inflammatory effect." (PMID 40343252, 2025). "In a preclinical study using colorectal cancer cells, it was demonstrated that TNF‐α regulates EMT, resulting in enhanced metastases of colorectal cancer cells." (PMID 40985344, 2025). "It has been shown to decrease oxidative stress markers and inflammatory cytokines such as TNF-α, CRF) and IL-6, promoting better postoperative recovery in laparoscopic colorectal cancer resection." (PMID 40951888, 2025). "TNFα plays an important role in increasing the phosphorylation and expression of STAT3 and its target genes related to cell survival and metastasis of colorectal cancer." (PMID 40558596, 2025). "We found that knockout of NSD2 significantly reduced the concentrations of IL‐6, TNF‐α, and TGF‐β1 in the serum of mice with colorectal cancer." (PMID 38400589, 2025). "To analyze the biological effects of TNF-α in CRC, we generated tumor cell secretome (TCS) and inflammatory TCS (iTCS) by treating colorectal cancer cells with TNF-α." (PMID 39310770, 2024). "The authors observed increased expression of IL-10 and IL-13 and decreased expression of IL-1β, IL-6, interferon gamma (IFN-γ), TNF-α, IL-12, and IGF-1 in peripheral blood mononuclear cells (PBMCs) derived from patients with colorectal cancer." (PMID 38957737, 2024). "EPHA2 was found to promote the formation of vasculogenic mimicry (VM) in colorectal cancer (CRC) via PI3K/AKT/mTOR and ERK1/2 signaling, and TNF plays a role in angiogenesis by synergistically inducing VEGF production with IL-1beta (IL1B)." (PMID 39596139, 2024). "In an in vivo model of AOM/DSS-induced colorectal cancer in C57BL/6 mice, 50 mg/kg and 100 mg/kg OLE reduced IL-6, TNF-α, and IFN-γ colon tissue levels, as well as COX-2 levels." (PMID 38540115, 2024). "In the current study, we show that in colorectal cancer cells, Pol III inhibition augments the cytotoxic and cytostatic effects of TNFα." (PMID 36900285, 2023). "Key pathways involved in Pathways in cancer, PI3K-Akt signaling pathway, Colorectal cancer, IL17 signaling pathway, TNF signaling pathway, and NF-κB signaling pathway." (PMID 37564983, 2023). "In the serum from 60 colorectal cancer (CRC) patients, we compared the differences in the expression of the levels of TGF-β, TNF-α, and PPAR-γ and in the expression of the main human miRNAs between right and left CRC." (PMID 37762927, 2023). "With respect to colorectal cancer (CRC), the effects of anti-TNFα mAb on tumors have been evaluated in vitro, in inflammatory carcinogenesis models, and in CRC subcutaneous allogeneic transplant models." (PMID 36996146, 2023). "HCT116 and LoVo human colorectal cancer cells were treated with DMSO, TNFα, RNA polymerase III inhibitor (ML-60218) alone, or a combination of TNFα and ML-60218." (PMID 36900285, 2023). "Here we show that in colorectal cancer cells, Pol III inhibition augments the cytotoxic and cytostatic effects of TNFα." (PMID 36900285, 2023). "As far as we know, this is the first study in which serum levels of pro-inflammatory cytokines (IL-1β, IL-6, TNF-α), inflammatory markers (ESR CRP and fibrinogen), and tumor markers (CEA and CA 19.9) have been compared in colorectal cancer." (PMID 38137862, 2023). "TNFα treatment stimulated ARID1A turnover in lung and colorectal cancer cells, A549 and HCT166 cells." (PMID 36435834, 2022). "In co-culture of colorectal cancer SL4 cells with RAW 264.7 cells, CXCL16 induced tumor cell apoptosis mediated by TNFα-expressing macrophages." (PMID 36686729, 2022).
colorectal cancer (continued). "For example, Th17 type cytokines, IL-6 and TNF-α can synergistically activate STAT3 and NF-κB pathways to promote the growth of colorectal cancer cells." (PMID 35842665, 2022). "The gene sets were also a part of pathways related to colorectal cancer, choline metabolism in cancer, HTLV-1 infection, TNF (tumor necrosis factor) signaling factor, and prolactin signaling pathway." (PMID 35039759, 2022). "Chrysin shows antiproliferative activity against human colorectal cancer cell line HCT-116, liver cancer cell line HepG2 and nasopharyngeal line CNE-1 to TNF-α-induced apoptosis." (PMID 35883797, 2022). "Reprogrammed interleukin-7 (IL-7)-IL-12-MSCs are reported to promote the activation of CAR-T immune cells and the release of IFN-γ and tumor necrosis factor-α (TNF-α), which markedly enhanced colorectal cancer cell death." (PMID 36439438, 2022). "Using a human colorectal cancer cell line, ONC201 was identified while screening small molecules that induce tumor necrosis factor (TNF)-related apoptosis-inducing ligand (TRAIL) gene expression." (PMID 34088951, 2021). "The enrichment analysis indicated that these key hub proteins were enriched in apoptosis, colorectal cancer, central carbon metabolism in cancer, pancreatic cancer, PI3K-Akt, estrogen, TNF, Sphingolipid, Neurotrophin, AMPK, and FoxO signaling pathway." (PMID 34093806, 2021). "In one of these, in patients with colorectal cancer, patients with high TH1 cytokine production, such as IFN‐γ and TNF‐α, had prolonged survival." (PMID 34633664, 2021). "In a mouse model of colorectal cancer, the use of AUR and its derivatives dramatically lowered the expression level of pro-inflammatory cytokines such as TNF-α, IL-1, and IL-6 and suppressed the activity of NF-κβ." (PMID 35432798, 2021). "The development of colorectal cancer (CRC) can be affected by various inflammatory mediators, such as tumor necrosis factor, nuclear factor kappa B, interleukins, and interferons." (PMID 33578830, 2021). "Both the TNF-alpha and the TGF-beta signaling pathways have been shown to determine the EMT phenotype of colorectal carcinomas, and can also synergistically converge and cooperate for EMT induction, as also revealed by our independent analyses." (PMID 33654197, 2021). "Significantly elevated expression of IL1-β, IL-6, IL-8, IL-10, IL-17, TNF-α, TGF-β, IFN-γ, and C-X-C motif chemokine ligand 1 (CXCL1) has been seen in colorectal cancer and other solid cancers like lung cancer." (PMID 32425932, 2020). "Gene expression of ALOX15 suppresses the TNF-α signaling pathway, IL-1β/NF-κB, and IL-6/STAT3, which play a major role in increasing colorectal cancer through chronic inflammation." (PMID 32986357, 2020). "In colorectal cancer cells, β-catenin regulates the activity of the NF-κB promoter, whereas inhibition of GSK-3β by lithium or siRNA potentiated TNF-induced expression of IL-6 and CCL2 in human microvascular endothelial cells." (PMID 33171974, 2020). "According to the results, these hub genes were predominantly involved in TNF, Toll-like receptor, NOD-like receptor, colorectal cancer and pathways in cancer signaling." (PMID 33059609, 2020). "In colorectal cancer patients, white blood cell count, platelet, ApoA, FFA, IL-6 and TNF-α increase significantly, while albumin, prealbumin and ApoE decreased significantly." (PMID 31788012, 2019). "To evaluate co-localization of miR-21 and TNF-α mRNA in budding cancer cells, we performed the combined assay, detecting miR-21, TNF-α mRNA and CK, on four frozen colorectal cancer samples with evident budding characteristics." (PMID 30999696, 2019).